SNAI1 (snail family transcriptional repressor 1)
Diseases named in the same sentence as SNAI1 in open-access papers (continued):
Sharing a sentence is not in itself a finding about the gene and the disease.
tumor (continued). "Since the initial description of the E-cadherin repressor SNAI1 as potential mediator of a more aggressive tumor phenotype, several studies have examined the potential consequences of EMT in SCC of the head and neck (HNSCC) in vitro and in vivo using a range of different methods." (PMID 20181105, 2010). "Among normal tissue constituents nuclear SNAI1 expression was most frequently seen in endothelial cells, and there was an impression of a more frequent SNAI1 positivity in vascular elements closer to the tumor." (PMID 20181105, 2010). "However, a small group of cases with SNAI1-positivity in more than 10% tumor cells (n = 4/46) was characterized by both significantly shorter EFS and DSS (p = 0.0259 and p = 0.0341, respectively)." (PMID 20181105, 2010). "SNAI1 nuclear staining was more frequent in stroma than in tumor cells." (PMID 20181105, 2010). "Several studies have shown that SNAI1 is found in the invasive regions of tumours." (PMID 19055748, 2008). "In this study we aimed to determine whether SNAI1 activity is correlated with expression of PA system components, and how this correlation can influence tumoural cell migration." (PMID 19055748, 2008). "In addition, we detected the protein expression levels of VRK1 and SNAI1 from mice tumor tissues." (PMID 40234378, 2025). "Additionally, the expression of TWIST1, SNAI1, FN1, and CDH2 also showed significant association with NUTF2, suggesting that NUTF2 may play a major tumor-promoting role in the Lumina A BRCA subtype." (PMID 35155261, 2022). "Moreover, based on the expression of EMT hallmark genes including SNAI2, N-cadherin, Vimentin, ZEB1, ZEB2, SNAI1, Fibronectin, TWIST1 and E-cadherin, we found that patients with high risk score distinctly exhibited a mesenchymal phenotype, suggesting a higher tumor malignancy." (PMID 36505846, 2022). "Similarly, knockdown of SNAI2 alone failed to revert EMT and suppressed the tumor initiation, in contrast to more potent effects associated with loss of SNAI1." (PMID 34063254, 2021). "Therefore, the cross-talk between SNAI1 and tumor microenvironment might be an important mechanism for the development and progression of GI cancers." (PMID 32833672, 2020). "The axis HOTAIR/miR-200c/SNAIL (or SNAI1, zinc finger transcription factor), involved in OvCa invasion, was demonstrated using transduced lentivirus-miR-200c, gain- or loss-of-function assays, EMT markers, and tumorigenicity of SKOV3 cells in xenograft tumor studies." (PMID 33238475, 2020). "(D) The mRNA expression of N-cad (Exo-3B, P < 0.0001; Exo-3B-KD, P = 0.0015), Snai1 (Exo-3B, P = 0.0011; Exo-3B-KD, P = 0.0010), β-catenin (Exo-3B, P = 0.0015; Exo-3B-KD, P = 0.1158) and Vimentin (Exo-3B, P = 0.1211; Exo-3B-KD, P = 0.7113) in tumor cells, which were treated with exosomes." (PMID 31477130, 2019). "(D) The relative mRNA expression of N-cad (Exo-3B, P = 0.0287; Exo-3B-KD, P = 0.0014), Snai1 (Exo-3B, P = 0.0004; Exo-3B-KD, P = 0.0014), β-catenin (Exo-3B, P < 0.0001; Exo-3B-KD, P = 0.0166) and Vimentin (Exo-3B, P = 0.0003; Exo-3B-KD, P = 0.0139) in ECs treated with exosomes from tumor cells." (PMID 31477130, 2019). "The influence of the methylation of EMT-associated genes (TWIST1, SNAI1 and SNAI2) and the clinico-histopathological features of invasive BC, namely, age, HR and HER2 status, tumour histology and Ki-67 proliferative index on tumour grade were assessed in a multivariate model." (PMID 30189837, 2018). "Hence, we could safely concluded that PHF8-mediated FIP200-dependent autophagy was crucial for degradation of E-cadherin, EMT and tumor metastasis, and complementary to transcriptional repression of E-cadherin by SNAI1 upregulation in HCC." (PMID 30180906, 2018).
tumor (continued). "It has been suggested that KLF4 together with SNAI1 may promote metastasis by inducing transdifferentiation of tumor cells into endothelial cells by an EMT-dependent mechanism, while other studies have suggested that KLF4 also can promote metastasis by EMT-independent mechanisms." (PMID 29765518, 2018). "Similarly, knockdown of SNAI1 in RD cells using two different shRNAs resulted in significantly reduced tumor growth in vivo when assessed by luciferase imaging at 21 days and after tumors were palpable (p < 0.001, two-way ANOVA followed by Dunnett's multiple comparisons test)." (PMID 28614716, 2017). "SPARC can also induce EMT by upregulating the expression of EMT regulatory transcription factors SNAI1/2 and ZEB1 thereby inducing changes in cellular phenotype to promote tumour progression." (PMID 39865173, 2025). "A heatmap analysis was conducted using a TCGA dataset of LUAD patients for TNFAIP6, PLK1, and mesenchymal markers including CDH2, SNAI1, and SNAI2 in paired normal tissue (left, normal) and adjacent tumor tissues (right, LUAD) depending on stages." (PMID 40860188, 2025). "In the subgroup of patient tumour samples with an elevated accumulation of IL‐11, EMT genes (SNAI1, AXL and TWIST1) and hypoxia factor 1 (HIF1A) were over‐expressed compared with the subtype with a lower accumulation of IL‐11." (PMID 40673604, 2025). "This remodeling of BCAA metabolism leads to enhanced expression of snail family transcriptional repressor 1 (SNAIL1), which promotes aggressive phenotypes and tumor progression in RCC models." (PMID 40465706, 2025). "The crosstalk of TGFβ with Wnt, NFkB, Notch or hypoxia signaling pathways orchestrates tumor-specific EMT progression through SMADS, SNAI1/2, TWIST, and ZEB1/2 factors." (PMID 39075581, 2024). "A strong positive correlation was detected between the expression of INHBA and EMT transcription factors SNAI1 (Rho = 0.62), SNAI2 (Rho = 0.82), and TWIST1 (Rho = 0.69) in the primary tumor." (PMID 38329386, 2024). "At the same time, the decrease in MMP-2, MMP-9 SNAI1 and TWIST1 protein levels in IL-22 + LY294002 cells indicated that inhibition of the PI3K/AKT signaling pathway reduced MMP expression, attenuating tumor cell invasion and metastasis." (PMID 39073546, 2024). "Numerous studies have clarified the molecular mechanisms by which SNAI1 regulates EMT, including the upregulation of matrix metalloproteinase genes such as MMP9, which degrade the basement membrane and stimulate tumor cell invasion." (PMID 39722890, 2024). "SNAI1, CDH1, and FN1 gene expression was detected more frequently in EPCAMlow than in EPCAM-negative primary tumor spots." (PMID 39456890, 2024). "Taken together, these results suggest that SNAI1 functionally regulates the expression of PIK3R2, thereby promoting tumor invasiveness." (PMID 39702326, 2024). "We have previously shown that SNAIL (SNAI1), an EMT inducing transcription factor that promotes tumor cell migration and invasion, is regulated by the action of DDR2 in tumors, post-transcriptionally." (PMID 37996700, 2024). "The named growth factors, in turn, activate SNAI1 and ERK MAPKs in the endothelial cells of lymphatic vessels, enhancing their proliferation and tumor lymphangiogenesis." (PMID 39329988, 2024). "Combined expression of WNT ligands (WNT3A, WNT4, WNT7B, WNT9A, WNT10A, WNT11) in BRCA patient tumours has a positive correlation (R = 0.27, p value = 0) with the combined expression of key EMT-inducing transcription factors SNAI1, SNAI2, ZEB1, ZEB2 and TWIST1." (PMID 38678032, 2024). "In particular, SNAI1 and FN1 were found to be positively correlated with EMT activation in more than half of the tumor types analyzed." (PMID 38144565, 2023).
tumor (continued). "The mRNA expression levels of RGS16, SNAI1, CDR2L, FRMD5, and FSTL3 were higher in tumor samples than that in adjacent normal tissues in TCGA-COAD cohort, suggesting that these five key genes participate in the progression of CC." (PMID 36925652, 2023). "Mechanistically, ZNF750 has been reported to mediate tumor-suppressive roles by regulating the expression of various downstream genes, such as TINCR, LAMC2, DANCR, FGF14, and SNAI1." (PMID 37365152, 2023). "TIMP1, PGF, FSTL3, SNAI1, and FOXC1 were highly expressed in CAFs with high stemness scores in the tumor intestinal tissues." (PMID 37017587, 2023). "SNAI1 and STC1 contribute to accelerating tumor progression in tumor growth, chemotherapy resistance, and immune environment suppression." (PMID 38033866, 2023). "Among these genes, Snail1 (coded by SNAI1) is an important transcriptional factor in EMT, which is a well-accepted biological process in tumor cell metastasis." (PMID 37122003, 2023). "miR-22 has been observed to target SNAI1 and inhibit EMT in tumor cells and their migration/invasion in a variety of cancers." (PMID 36980876, 2023). "This is consistent with previous studies linking ZEB1, SNAI1 and TWIST1 with a mesenchymal phenotype of tumor cells in CRC." (PMID 35565409, 2022). "Tumor cells with increased endogenous levels of Snail Family Transcriptional Repressor 1 (SNAI1), the major EMT transcription factor, exhibit an increased tumor-initiating ability and metastatic potential." (PMID 36612206, 2022). "Further study is needed to validate this regulatory axis in tumor samples and to characterize the redundant and distinct biological functions of FOXQ1 and SNAI1 in cancer and normal physiology." (PMID 36713812, 2022). "The results showed that after treatment with lapatinib for 2 h, the SNAI1 and SNAI2 expression levels in most tumor cell types were decreased, as was their survival ability." (PMID 35898399, 2022). "SNAIL (also known as SNAI1), a zinc-finger transcriptional repressor, modulates EMT during tumour progression." (PMID 36310592, 2022). "The expression levels of MYC, NR5A2, SNAI1, TWIST1, and STK11 were significantly higher in tumor-adjacent tissues than in the matched EC samples, and this difference was not influenced by the content of cancer cells in cancer-adjacent tissues." (PMID 36140779, 2022). "Snai1 is overexpressed in a variety of tumors, and its overexpression induces EMT of tumor cells and promotes metastasis and invasion." (PMID 35434126, 2022). "The m6A levels in subcutaneous xenograft tumours in the LV-FTO group decreased, and the mRNA expression of SNAI1 was downregulated." (PMID 36358640, 2022). "Previous studies on SNAI1 and/or TWIST1 in EC mostly relied on their immunohistochemical evaluation in tumor cells in the context of clinical variables, and increased SNAI1 and TWIST1 expression has been linked to EC progression or poor prognosis." (PMID 36140779, 2022). "Knockdown of major TFs of the TGF-β pathway, SNAI1/2, and SMAD4, led to decreased FN1 expression, consequent EMT inhibition, and decreased tumor cell motility." (PMID 35216235, 2022). "Our data showed a higher expression of both SNAI1 and TWIST1 in EC-adjacent tissues than in the matched tumor samples." (PMID 36140779, 2022). "In EC, the expression of cancer-promoting genes, MYC, NR5A2, SNAI1, and TWIST1, was found to be significantly higher in tumor-adjacent tissues than in the matched tumors." (PMID 36140779, 2022). "In this study, we found that miR-30e-5p functions as a tumor inhibitor in the regulation of proliferation, apoptosis, migration, and EMT of PCa cells by targeting SNAI1, suggesting that miR-30e-5p and SNAI1 play crucial roles in PCa." (PMID 35300562, 2022). "Taken together, our results demonstrate that knockdown of SNAI1 in patient-derived HGSOC samples in vitro and in vivo results in restoration of let-7, decreased stemness, and reduced tumor burden." (PMID 33806868, 2021).
tumor (continued). "Compared with the primary tumor, in the metastasis group, the mesenchymal markers (CDH2, VIM, TWIST1, SNAI1, ZEB1) and ferroptosis drivers increased, and the epithelial marker CDH1 and ferroptosis suppressor decreased." (PMID 35127731, 2021). "Enhanced CCA migration was associated with induction in key EMT genes and several crucial EMT genes and inducers of EMT such as GLI, PTCHD1, SNAI1, SNAI2, and SHH, in tumor cells in response to inflamed LECs." (PMID 34831316, 2021). "Simultaneous inactivation of Snai1 and Twist induces a shift of the EMT-equilibrium to a more epithelial-like state in the primary tumor of KPC mice while enhancing liver metastases." (PMID 34888306, 2021). "In line with downregulation of FBXL5 in tumor cells of PDAC, we found that both IRP2 and SNAI1 were upregulated." (PMID 34733841, 2021). "SNAI1 participates in the stimulation of epithelial-to-mesenchymal transition (EMT) and exerts a vital role in tumor drug resistance, cellular proliferation inhibition, survival, and movement." (PMID 33937013, 2021). "SNAI1, a zinc-finger containing transcription factor, induces EMT by direct suppression of E-cadherin (CDH1) transcription during development or tumor progression." (PMID 34335956, 2021). "Next, we evaluated the specific promoter methylation of the four genes from the TGFβ signaling pathway (TGFBR2, SMAD4, SMAD7 and SNAI1) evaluated in SNU449 cells in resected human HCC tumors, as well as in the surrounding non-tumor tissues." (PMID 34571856, 2021). "Recent research suggests that autophagy degrades SNAI1 in cancer cells via LC3 and/or (sequestosome 1) SQSTM1, thereby inhibiting tumor progression." (PMID 33937013, 2021). "However, acetylated SNAI1 can act as an activator to induce tumor necrosis factor alpha (TNF-α), C-C motif chemokine ligand 2 (CCL2), and C-C motif chemokine ligand 5 (CCL5) gene transcription, which in turn promote carcinoma progression and the recruitment of tumor-associated macrophages (TAMs)." (PMID 34298613, 2021). "While NOTCH signaling is centrally involved in cell proliferation, differentiation, and survival, SNAI1 is involved in the induction of EMT processes, which are critical for the shedding of circulating tumor cells and metastasis." (PMID 34638315, 2021). "Snail family transcriptional repressor 1 (Snai1) has been documented as the key modulator of EMT, as well as in regulation of GBM tumor progression." (PMID 34337348, 2021). "SNAI1 recruits the p300 activator complex to the VEGF and Sox2 promoters to stimulate their expression, leading to endothelium generation and tumor growth." (PMID 34681726, 2021). "They showed a strong expression of the mesenchymal marker vimentin and N-cadherin, promoting cell migration and metastasis as well as the HNSCC tumor stem cell marker CD44 and overexpression of the oncogenic transcription factor Snai1." (PMID 34884892, 2021). "In the tumour stroma‐derived EVs, enrichment of IL1A, IL1B, and SNAI1 was consistent with a more inflammatory stromal phenotype typically associated with disease." (PMID 34596356, 2021). "Compared to controls, tumor displaying lower SNAI1, PECAM1 and VIM and higher TP63, KRT14, KRT5 and PTPRC (CD45) RNAs (PyMT-VE-CadhSnail1KO tumor signature) presented a longer overall survival, strengthen our mice results." (PMID 34335957, 2021). "Oncomine datasets demonstrated CDH1, CDH2, SNAI1, SNAI2, VIM, TWIST1 in 20 types of cancers between tumor and normal tissues." (PMID 31915310, 2020). "A large number of genes that function as tumour and growth suppressors, such as PHACTR4 and ARID4A, as well as genes that correspond to chemotherapy/radiotherapy response genes, such as SNAI1 and SNX1, were overexpressed." (PMID 32543350, 2020). "SNAI1 mRNA and HSA/MIR203 was higher and lower, respectively, in EC patients compared to tumor-adjacent normal tissues." (PMID 32760222, 2020).
tumor (continued). "It is well known that SNAI1, SNAI2, ZEB1, ZEB2, TWIST1 and TWIST2 are key transcription factors involved in EMT in various types of cancers, and they contribute to enhanced tumour cell migration, invasion and metastasis capacities." (PMID 32488136, 2020). "The correlations of ZNF750 with SNAI1, VIM, CDH2 and CDH1 were verified with our RNA sequencing data of 155 paired of ESCC and matched non-tumor tissues." (PMID 32042337, 2020). "The distribution of mRNA expression levels of STAMBPL1 and SNAI1 was analysed with split-violin plots, which shows the expression and the co-occurrence of STAMBPL1 (red) with SNAI1 (green) in each tumour type, including LUAD and BRCA." (PMID 32636467, 2020). "SNAIL (zinc finger protein SNAI1) is a protein involved in the process of invasion and metastasis of tumor cells." (PMID 32260235, 2020). "We further compared the mRNA expression of CDH1, CDH2, SNAI1, SNAI2, VIM, TWIST1 between ccRCC tumor samples and adjacent normal tissues respectively based on RNA-sequence data from TCGA database." (PMID 31915310, 2020). "For clinical applications, BK697, a chemical inhibitor of FIRΔexon2, suppressed FIR family expression and tumor cell growth with SAP155 and E-cadherin suppression and increased Snai1 expression." (PMID 32071290, 2020). "As a tumor metastasis regulator, CAR10 enhances the expression of SNAI1 and SNAI2 via directly sponging miR-30 and miR-203 to promote EMT." (PMID 30617305, 2019). "PI3K/Akt pathway can activate Snai1 and slug expression that has been correlated with EMT and invasive tumor types through repression of E-cadherin and occludin expression mediated by Snai1/SMAD3/SMAD4 complex." (PMID 31798766, 2019). "More attention has been paid to the roles of PHF8 in promoting tumor metastasis and EMT by co-transcriptionally activating SNAI1 and VIM expression, which was consistent with the current results." (PMID 30180906, 2018). "Prevention of tumor growth was related with suppression of COX-2/MMP2, ZEB1 and zinc finger protein SNAI1 (SNAI1)." (PMID 30445746, 2018). "Circulating tumor cells (CTCs) have elevated levels of the key transcription factors ZEB1, SNAI1, and TWIST and their downstream targets." (PMID 29320425, 2018). "It was reported that the tumor suppressor miR-375 represses CIP2A mRNA through multiple miRNA-mRNA interactions, and it is in turn negatively regulated by SNAI1 (Snail)." (PMID 29228564, 2017). "VIM, TWIST1, AKT2, and SNAI1 are expressed in CRC pathological tissues, where they promote tumor metastasis by inducing the EMT process." (PMID 28030836, 2017). "For instance, another SNAI family member, SNAI1, initiates the EMT program and regulates cancer metastasis in tumor cells." (PMID 29041931, 2017). "Then, we compared the mRNA levels of several TGF-β-related EMT-regulators including SNAI1, SNAI2, HMGA2, FOSL1, SP1, ZEB1, ZEB2 (SIP1), and TWIST1 in primary tumor tissues of MDA-MB-231-xenografted mice." (PMID 26462028, 2015). "In this study, we used immunohistochemistry to study the expression of a panel of transcription factors (TWIST1, SNAI1/2, ZEB1 and ZEB2) and other genes intimately related to EMT (CDH1 and LAMC2) at the invasive tumor front of OSCC tissues." (PMID 26214683, 2015). "The activities of the transcription factors Twist1/2, SNAI1/2, AP1, NF-κB, and Stat3 were suppressed by doxycycline, which reversed EMT and inhibited signal transduction, thereby suppressing tumor growth and metastasis." (PMID 26512779, 2015). "Expression of SNAI1/2, ZEB2 and TWIST1 were observed in the nucleus as well as the cytoplasm of epithelial cells, however, only nuclear staining in normal and tumor epithelial cells was evaluated as these proteins are expected to regulate transcription." (PMID 26214683, 2015).